FBXO6 (F-box protein 6)
Description:
Substrate-recognition component of some SCF (SKP1-CUL1-F-box protein)-type E3 ubiquitin ligase complexes. Involved in endoplasmic reticulum-associated degradation pathway (ERAD) for misfolded lumenal proteins by recognizing and binding sugar chains on unfolded glycoproteins that are retrotranslocated into the cytosol and promoting their ubiquitination and subsequent degradation. Able to recognize and bind denatured glycoproteins, which are modified with not only high-mannose but also complex-type oligosaccharides. Also recognizes sulfated glycans. Also involved in DNA damage response by specifically recognizing activated CHEK1 (phosphorylated on 'Ser-345'), promoting its ubiquitination and degradation. Ubiquitination of CHEK1 is required to ensure that activated CHEK1 does not accumulate as cells progress through S phase, or when replication forks encounter transient impediments during normal DNA replication.
Synonyms: FBG2; FBS2; FBX6; Fbx6b
Tractability: PROTAC: ubiquitination databases record sites on it; its protein half-life has been measured.
Gene: Protein-coding gene on chromosome 1 (11,664,189 to 11,674,354, forward strand). Ensembl gene ENSG00000116663.
Subcellular location: Cytoplasm
Pathways (Reactome):
Metabolism of proteins: Association of TriC/CCT with target proteins during biosynthesis; Neddylation
Immune System: Antigen processing: Ubiquitination & Proteasome degradation
Gene Ontology:
Molecular function: protein binding; ubiquitin protein ligase activity; carbohydrate binding
Biological process: SCF-dependent proteasomal ubiquitin-dependent protein catabolic process; DNA damage checkpoint signaling; DNA repair; ERAD pathway; glycoprotein catabolic process; proteolysis; protein ubiquitination; ubiquitin-dependent protein catabolic process
Cellular component: cytoplasm; SCF ubiquitin ligase complex; cytosol; endoplasmic reticulum quality control compartment
Genetic constraint (gnomAD): Loss-of-function variants: 14 observed, 26.92 expected, observed/expected ratio (o/e) 0.52, 90% interval 0.34 to 0.81. The upper end of that interval is the gene's LOEUF score, 0.81, which puts it in group 3 of 6, group 1 being the genes least tolerant of losing a copy. Missense variants: 370 observed, 399.42 expected, observed/expected ratio (o/e) 0.93, 90% interval 0.85 to 1.01. Synonymous variants: 138 observed, 163.78 expected, observed/expected ratio (o/e) 0.84, 90% interval 0.73 to 0.97.
Homologues: Orthologues: chimpanzee FBXO6 (99% identical), dog FBXO6 (77% identical), macaque FBXO6 (77% identical), guinea pig FBXO6 (75% identical), pig FBXO6 (74% identical), rabbit FBXO6 (72% identical), rat Fbxo6 (70% identical), mouse Fbxo6 (68% identical). Paralogues in human: FBXO44 (65% identical), FBXO2 (43% identical), FBXO27 (35% identical), FBXO17 (30% identical), NCCRP1 (24% identical).
Diseases named in the same sentence as FBXO6 in open-access papers:
FBXO6 is named in the same sentence as 28 diseases in open-access papers, as found by Europe PMC text mining. Sharing a sentence is not in itself a finding about the gene and the disease. The quoted sentences say what the papers report.
ovarian carcinoma (6 papers, 2021 to 2022). A malignant neoplasm originating from the surface ovarian epithelium. "Here we found that FBXO6 was overexpressed in ovarian cancer tissues and the high expression of FBXO6 was associated with the poor survival of ovarian cancer patients at advanced stages." (PMID 33767133, 2021). "Together, these results suggest that the downregulation of RNASET2 protein in ovarian cancer might be caused by FBXO6 overexpression." (PMID 33767133, 2021). "Of note, they reported the interaction of the RNASET2 protein with FBXO6 in two human ovarian cancer cell lines (A2780 and OVCAR3)." (PMID 36012339, 2022). "The ubiquitination and degradation of FBXO6-mediated RNASET2 regulated the progress of ovarian cancer." (PMID 35938021, 2022). "Conversely, FBXO6 overexpression led to a marked decrease in RNASET2 protein expression in a dose-dependent manner, clearly suggesting that FBXO6 is involved in the degradation of RNASET2 protein in both ovarian cancer cell models." (PMID 36012339, 2022). "Accordingly, a subsequent survival analysis on the clinical ovarian cancer database indicated a strong correlation between higher FBXO6 expression and the overall survival of ovarian cancer patients at advanced stages." (PMID 36012339, 2022). "Our results not only reveal a regulatory mechanism of FBXO6 on RNASET2 protein but also uncover that the oncogenic effect of FBXO6 in ovarian cancer partly depends on the degradation of RNASET2." (PMID 33767133, 2021). "Our data further revealed a critical role of the FBXO6-RNASET2 axis in the regulation of ovarian cancer cell proliferation, migration, invasion in vitro, and tumor formation in nude mice in vivo." (PMID 33767133, 2021). "Through transwell and scratch experiments, we further confirmed that FBXO6 silencing significantly inhibited the migration and invasion ability of ovarian cancer cells." (PMID 33767133, 2021). "Analysis of The Cancer Genome Atlas dataset revealed that FBXO6 was significantly upregulated in ovarian cancer tissues (88 normal vs. 426 ovarian cancer, p < 0.05)." (PMID 33767133, 2021). "In the present study, we further revealed an oncogenic role of FBXO6 in ovarian cancer by targeting tumor suppressor RNASET2 for destruction." (PMID 33767133, 2021). "Our results revealed that silencing the expression of RNASET2 in FBXO6-depleted ovarian cancer cells promoted tumor growth in vivo." (PMID 33767133, 2021). "Through analysis of the TCGA dataset, we found that FBXO6 was significantly increased in ovarian cancer tissues and the high expression of FBXO6 was related to the poor overall survival (OS) of ovarian cancer patients at advanced stages." (PMID 33767133, 2021). "To understand the clinic relevance of FBXO6, we investigated its expression in ovarian cancer tissues." (PMID 33767133, 2021). "A survival analysis of the clinical ovarian cancer database indicated a correlation between higher FBXO6 expression and the overall survival in ovarian cancer patients at advanced stages (stage 2 + 3, stage 3 + 4, or stage 2 + 3 + 4) were observed." (PMID 33767133, 2021). "The overexpression of FBXO6 in ovarian cancer samples (68/88, 77.3%) was confirmed by the IHC analysis." (PMID 33767133, 2021). "We next performed IHC analysis to evaluate the potential association between FBXO6 and RNASET2 in 88 human ovarian cancer specimens." (PMID 33767133, 2021). "Moreover, RNASET2 protein has been reported to be targeted for FBXO6 unbiquitin-dependent protein degradation in ovarian cancer suggesting additional regulatory mechanism contribute to RNASET2 protein turnover." (PMID 36466822, 2022). "FBXO6 was related to ovarian cancer treatment and glycoprotein quality control." (PMID 34675963, 2021). "We propose that inhibition of FBXO6 might represent an effective therapeutic strategy for ovarian cancer treatment." (PMID 33767133, 2021).
ovarian carcinoma (continued). "Depletion of FBXO6 promoted ovarian cancer cells proliferation, migration, and invasion, which could be partially reversed by RNASET2 silencing." (PMID 33767133, 2021). "Furthermore, a nude mice model was used to investigate whether FBXO6 affects the oncogenic potential of ovarian cancer in vivo." (PMID 33767133, 2021). "We next investigated whether FBXO6 regulates ovarian cancer progress through RNASET2 degradation." (PMID 33767133, 2021). "Thus, based on these clues, we believe that inhibition of FBXO6 may represent an effective strategy for the treatment of ovarian cancer." (PMID 33767133, 2021). "FBXO6 directly interacts with the tumor suppressor gene RNASET2 to target it for ubiquitin-dependent degradation, thus functioning as an oncogene in ovarian cancer." (PMID 35368888, 2022). "An inverse correlation between the protein levels of FBXO6 and RNASET2 was observed in clinic ovarian cancer samples." (PMID 33767133, 2021). "These phenomena were also observed in A2780 FBXO6−/− cells compared with FBXO6+/+ cells, suggesting a regulatory role of FBXO6 in the control of ovarian cancer cells proliferation." (PMID 33767133, 2021). "However, the impaired migration and invasion abilities of FBXO6-depleted ovarian cancer cells were largely restored when RNASET2 was simultaneously silenced, suggesting a functional interplay between FBXO6 and RNASET2 proteins in ovarian cancer cells." (PMID 33767133, 2021). "Therefore, our results reveal a previously unknown FBXO6-RNASET2 axis, which may contribute to the development of ovarian cancer." (PMID 33767133, 2021). "Thus, our data revealed a novel FBXO6-RNASET2 axis, which might contribute to the development of ovarian cancer." (PMID 33767133, 2021). "Finally, an IHC survey on 88 human ovarian cancer specimens unveiled a negative correlation between FBXO6 and RNASET2 proteins expression, further pointing at a causal link between downregulation of RNASET2 protein in ovarian cancer and FBXO6 overexpression." (PMID 36012339, 2022). "We further found that there was a negative correlation between RNASET2 and FBXO6 protein in clinical ovarian cancer samples, suggesting that blocking the interaction between FBXO6 and RNASET2 might be a novel anti-ovarian cancer strategy." (PMID 33767133, 2021). "Moreover, a negative correlation between FBXO6 and RNASET2 proteins was observed in those ovarian cancer samples (χ2 = 13.41, P < 0.001)." (PMID 33767133, 2021).
gastric cancer (4 papers, 2009 to 2021). A primary or metastatic malignant neoplasm involving the stomach. "FBXO6 protein can promote the growth and proliferation of gastric cancer cells and normal gastric cells." (PMID 35111198, 2021). "Li and his colleagues report that FBXO6 can significantly promote the growth and proliferation of gastric cancer cells and normal gastric cells and change the cell cycle of them." (PMID 29340037, 2017). "FBXO6 has also been shown to promote growth and proliferation of gastric cancer cells compared with control cells that do not express the protein." (PMID 22087255, 2011).
non-small cell lung carcinoma (3 papers, 2021 to 2023). A group of at least three distinct histological types of lung cancer, including non-small cell squamous cell carcinoma, adenocarcinoma, and large cell carcinoma. "FBXO6 also inhibits cell proliferation, induces apoptosis, and enhances cell sensitivity to cisplatin by Chk1 in non-small cell lung cancer." (PMID 36998461, 2023). "FBXO6 controls the degradation of checkpoint kinase 1 (Chk1) and confers the sensitivity to certain anticancer drugs, including camptothecin, in tumor cells, such as non-small cell lung cancer, GBM, and breast cancer." (PMID 36998461, 2023). "Furthermore, it has been demonstrated that FBXO6 inhibits Chk1 activation in non-small cell lung cancer, increasing cisplatin sensitivity." (PMID 36147499, 2022).
asthma (1 paper, 2023). "Fbxo6 was identified as a hub gene and served an important role in the process of asthma." (PMID 36217277, 2023).
autoimmune disease (1 paper, 2021). A disorder resulting from loss of function or tissue destruction of an organ or multiple organs, arising from humoral or cellular immune responses of the individual to their own tissue constituents. "Thus, it is important to determine whether FBXO6 is also involved in regulating autoimmune diseases or neurodegenerative diseases." (PMID 33767133, 2021).
bladder cancer (1 paper, 2022). "Contrary to bladder epithelial cells, bladder cancer cells expressed significantly higher levels of FBXO6 and TMEM229B genes." (PMID 36468020, 2022). "To test the study hypothesis, in human bladder epithelial cells, we detected the expression of FBXO6, OAS1, and TMEM229B genes, as well as three different bladder cancer cell lines by using RT-qPCR technique." (PMID 36468020, 2022).
breast carcinoma (1 paper, 2023). "Using multivariate Cox analysis, FBXO6, PMAIP1, ERP27, and CHAC1 were identified as independent prognostic factors in patients with breast cancer." (PMID 37313465, 2023). "Western-blot analysis revealed that the protein expression of FBXO6, PMAIP1, ERP27, and CHAC1were significantly higher in breast cancer cell lines(SKBR-3, MDA-MB-231, T-47D)than in normal mammary epithelial cell line MCF-10A." (PMID 37313465, 2023). "For example, FBXO6 expression did not significantly differ with breast cancer stage, while PMAIP1 expression was lower in late stages." (PMID 37313465, 2023).
breast tumors (1 paper, 2023). "We compared the expression profiles of 272 ERS-related genes in primary breast tumors and normal breast tissue and identified FBXO6, PMAIP1, ERP27, and CHAC1 as independent prognostic factors with established risk models (defining the risk scores as ERScore) and model validation." (PMID 37313465, 2023).
cervical cancer (1 paper, 2022). A primary or metastatic malignant neoplasm involving the cervix. "Further studies are necessary to elucidate mechanism of SP140/FBXO6 in cervical cancer." (PMID 35368888, 2022).
chondrosarcoma (1 paper, 2020). A malignant cartilaginous matrix-producing mesenchymal neoplasm arising from the bone and soft tissue. "By co-immunoprecipitation, we confirmed that FBXO6 could bind to MMP14 in both ATDC5 and SW1353 chondrosarcoma cell line." (PMID 32409323, 2020).
disc degeneration (1 paper, 2023). "MiR-133a-5p expression aggravates IVD degeneration by targeting and inhibiting FBXO6, a protein highly expressed in healthy discs and progressively downregulated in relation to disc degeneration severity." (PMID 36768184, 2023).
lung carcinoma (1 paper, 2020). "Previous studies have demonstrated that FBXO6 inhibits tumor invasion in gastric and lung cancer; however, the underling mechanisms were not clear." (PMID 33330025, 2020).
osteoarthritis (1 paper, 2023). A noninflammatory degenerative joint disease occurring chiefly in older persons, characterized by degeneration of the articular cartilage, hypertrophy of bone at the margins and changes in the synovial membrane. "The human osteoarthritis samples and several mouse osteoarthritis models were used to detect the expression of FBXO6." (PMID 37359559, 2023). "This study showed that FBXO6 was downregulated in the cartilage from aged mouse samples, spontaneous osteoarthritis samples, ACLT (anterior cruciate ligament transaction)-induced osteoarthritis samples." (PMID 37359559, 2023). "Osteoarthritis process was accelerated in mice with cartilage conditional knockout or global knockout of FBXO6." (PMID 37359559, 2023). "Overall, upregulation of FBXO6 attenuated post-injury osteoarthritis development, suggesting that induction of FBXO6 in cartilage could be a useful strategy for treating osteoarthritis." (PMID 37359559, 2023). "explored the effects of FBXO6 on the osteoarthritis pathogenesis." (PMID 37359559, 2023).
pneumonia (1 paper, 2023). An acute, acute and chronic, or chronic inflammation focally or diffusely affecting the lung parenchyma, caused by an infection in one or both of the lungs (by bacteria, viruses, fungi, or mycoplasma.). "There are few studies regarding the role of FBXO6 in IAV‐induced pneumonia at present." (PMID 36217277, 2023).
tumor (9 papers, 2009 to 2026). "In vivo xenograft models further validate these findings: FBXO6 overexpression reduces tumor growth, Ki67 levels, and ITGB1-associated signaling." (PMID 41857001, 2026). "Additional rescue experiments show that FBXO6 counteracts the tumor-promoting effects of ITGB1 overexpression." (PMID 41857001, 2026). "Loss of SP140 in CESC cells downregulated the DNA repair gene FBXO6, which resulted an increased DNA repair and decreased generation of tumor-specific antigens." (PMID 35368888, 2022). "Genes involved in DNA damage response were differentially up-regulated in the sensitive tumours (FBXO6, RFC5, SOD2) suggesting that preparedness for keeping DNA undamaged promotes sensitivity when encountering a drug that causes DNA damage (CHO)." (PMID 25881228, 2015). "We found that KO of FBXO6 significantly decreased the tumor volume and tumor weight." (PMID 33767133, 2021). "Finally, FBXO6 has been reported to play a role in cell cycle control, inactivating S-phase and spindle checkpoints, and might contribute to increase tumor cell resistance to certain anticancer drugs." (PMID 34768773, 2021).
cancer (8 papers, 2011 to 2023). A tumor composed of atypical neoplastic, often pleomorphic cells that invade other tissues. "Impaired expression of FBXO6 (also called FBG2) increases the therapeutic resistance in cancer cells by inducing the degradation of target molecules in ubiquitin‐mediated cellular pathways." (PMID 33622332, 2021). "Other genes, such as ALOXE3, HBQ1, KREMEN2, SYT13, DOK7, CDC5L, and FBXO6, have been reported in several cancers." (PMID 28404969, 2017). "One plausible explanation for these observations is that NCCRP1 and FBXO6 are needed to target certain glycoproteins that affect the cell cycle for degradation and that the proliferation of cancer cells is impaired when this function is inhibited." (PMID 22087255, 2011). "FBXO6 (F-box protein 6, FBG2) is a substrate recognition component of certain SCF (SKP1, CUL1, and F-box protein)-type E3 ubiquitin ligases involved in the degradation of ER-associated proteins, and its role in cancer is highly complex." (PMID 36147499, 2022). "FBXO6 might contribute to genome instability during PC progression; genome instability is an essential oncogenic factor of PC and other cancer types." (PMID 33578925, 2021). "We analyzed the expression of the four independent prognostic factors (FBXO6, PMAIP1, ERP27, and CHAC1) in BRCA and 32 other cancer types and observed that all four genes were highly expressed in BRCA." (PMID 37313465, 2023). "Among the FASTKs interactors involved in cancer development, the best understood ones are EGFR, NTRK1 and FBXO6." (PMID 34768773, 2021).
infection (1 paper, 2023). The state of being infected such as from the introduction of a foreign agent such as serum, vaccine, antigenic substance or organism. "To further investigate the reason of the decrease of AMs in WT mice, we detected both the proliferation and apoptosis frequencies of AMs in the lungs of Fbxo6−/− and WT mice after infection with PR8 for 3 days." (PMID 36217277, 2023).
neurodegenerative disease (1 paper, 2021). A disorder of the central nervous system characterized by gradual and progressive loss of neural tissue and neurologic function. "Together, these reports indicate that FBXO6 might also be involved in the development of neurodegenerative diseases at least by regulating the stability of RNASET2 protein." (PMID 33767133, 2021).
FBXO6 also shares sentences with these, for which no sentence is quoted: colon cancer (1 paper); colorectal cancer (1); COVID-19 (1); dysplasia (1); gastric adenocarcinoma (1); inflammation (1); ovarian tumors (1); Sepsis (1); small cell lung carcinoma (1); viral infection (1).